ENSG00000288608 (novel protein)
Synonyms: SLC4A2uORF; LOC128092247
Gene: Protein-coding gene on chromosome 7 (151,061,928 to 151,061,978, forward strand). Ensembl gene ENSG00000288608.
Genetic constraint (gnomAD): Loss-of-function variants: 0 observed, 0.0826 expected, observed/expected ratio (o/e) 0, 90% interval 0 to 1.89. That is too few expected variants to judge how well the gene tolerates losing a copy. Missense variants: 16 observed, 12.23 expected, observed/expected ratio (o/e) 1.31, 90% interval 0.88 to 1.85. Synonymous variants: 3 observed, 2.51 expected, observed/expected ratio (o/e) 1.19, 90% interval 0.49 to 1.9.